ARF5 (ARF GTPase 5)
Description:
GTP-binding protein involved in protein trafficking. Contributes to vesicle budding and uncoating at the Golgi apparatus. Regulates mTORC1 activity at the plasma membrane by promoting its recruitment to membrane ruffles, facilitating activation via the PI3K/Akt signaling pathway. Acts as an early responder to lysosomal damage and participates in lysosomal quality control pathways. (Microbial infection) Functions as an allosteric activator of the cholera toxin catalytic subunit, an ADP-ribosyltransferase.
Tractability: Small molecule: a structure with a bound ligand is known. Antibody: its Gene Ontology location is reachable by antibodies, with medium confidence. PROTAC: ubiquitination databases record sites on it; its protein half-life has been measured.
Gene: Protein-coding gene on chromosome 7 (127,588,370 to 127,591,700, forward strand). Ensembl gene ENSG00000004059.
Subcellular location: Cell membrane; Golgi apparatus; Cytoplasm, perinuclear region; Lysosome membrane; Golgi apparatus, trans-Golgi network membrane
Pathways (Reactome):
Vesicle-mediated transport: COPI-dependent Golgi-to-ER retrograde traffic; COPI-mediated anterograde transport
Gene Ontology:
Molecular function: protein binding; GTP binding; GTPase activity
Biological process: lysosomal membrane organization; positive regulation of TOR signaling; retrograde vesicle-mediated transport, Golgi to endoplasmic reticulum; intracellular protein transport
Cellular component: extracellular exosome; Golgi apparatus; lysosomal membrane; plasma membrane; cytoplasm; perinuclear region of cytoplasm
Genetic constraint (gnomAD): Loss-of-function variants: 10 observed, 24.75 expected, observed/expected ratio (o/e) 0.4, 90% interval 0.25 to 0.69. The upper end of that interval is the gene's LOEUF score, 0.69, which puts it in group 2 of 6, group 1 being the genes least tolerant of losing a copy. Missense variants: 135 observed, 228.99 expected, observed/expected ratio (o/e) 0.59, 90% interval 0.51 to 0.68. Synonymous variants: 102 observed, 91.39 expected, observed/expected ratio (o/e) 1.12, 90% interval 0.95 to 1.32.
Homologues: Orthologues: chimpanzee ARF5 (100% identical), dog ARF5 (100% identical), macaque ARF5 (100% identical), mouse Arf5 (100% identical), pig ARF5 (100% identical), rabbit ARF5 (100% identical), guinea pig ARF5 (98% identical), zebrafish ARF5 (94% identical), zebrafish arf5 (93% identical), Caenorhabditis elegans arf-5 (84% identical), Drosophila melanogaster Arf4 (84% identical). Paralogues in human: ARF4 (88% identical), ARF1 (81% identical), ARF3 (79% identical), ARF6 (64% identical), ARL1 (58% identical), TRIM23 (56% identical), ARL4C (48% identical), ARL2 (46% identical), ARL4A (46% identical), ARL3 (44% identical), ARL14 (44% identical), ARL5A (44% identical), and 18 more.
Diseases named in the same sentence as ARF5 in open-access papers:
ARF5 is named in the same sentence as 17 diseases in open-access papers, as found by Europe PMC text mining. Sharing a sentence is not in itself a finding about the gene and the disease. The quoted sentences say what the papers report.
glioblastoma (2 papers, 2023 to 2024). The most malignant astrocytic tumor (WHO grade IV). "AGAP2 with regulatory activity on Arf1 and Arf5 enhances cancer cell survival, migration, and invasion in glioblastoma." (PMID 37182141, 2023).
hypophysis (2 papers, 2023 to 2024). "Both Wuschel-related Homeobox 9 (WOX9) and ARF5/MP are required for hypophysis specification and primary root formation, with mutations in either WOX9 or ARF5/MP resulting in defective stem cell niche establishment of the primary root." (PMID 38903418, 2024). "The embryonic root initiation process greatly depends on the antagonistic interaction between MP/ARF5 and its repressor BDL/IAA12 protein, and both the loss-of-function mp/arf5 and gain-of-function bdl/iaa12 mutants are defective in hypophysis specification." (PMID 37450945, 2023). "Likewise, WRKY23 acts downstream of ARF5–BDL/IAA12 during embryogenesis and formation of the hypophysis." (PMID 37450945, 2023).
prostate carcinoma (2 papers, 2021 to 2023). A carcinoma that arises from epithelial cells of the prostate gland. "We reported that in prostate cancer cells, the small GTPases ARF5 and ARF6 are required to maintain invasive protrusion formation in 3D culture." (PMID 37577760, 2023). "Elevation in IQSEC1, ARF5 and ARF6 levels was associated with clinical outcome in prostate cancer across 12 studies, representing 2910 patients." (PMID 33712589, 2021). "We examined the association of IQSEC1, ARF5, and ARF6 elevation with frequent genomic alterations in prostate cancer." (PMID 33712589, 2021).
breast carcinoma (1 paper, 2018). "Using inteGREAT, we also identified ANXA1 and ARF5 to be putative biomarkers for basal and luminal breast cancer subtypes with potential prognostic significance." (PMID 29971090, 2018). "Conversely, our RNA-seq experiments in breast cancer cell lines confirmed that ARF5 is highly expressed in MCF-7 luminal cells, but not expressed in basal cell lines." (PMID 29971090, 2018).
COVID-19 (1 paper, 2024). A disease caused by infection with severe acute respiratory syndrome coronavirus 2. "Through WGCNA and GSEA analysis, we further confirmed that ARF5 is involved in splicing complex, ribosome synthesis and function, intracellular material transport and other pathways, and is related to the progress of some neuropathy diseases, COVID-19, nonalcoholic fatty liver and other diseases." (PMID 38617932, 2024). "Through WGCNA analysis, the expression of ARF5 in HCC may be involved in many cellular processes that consume a lot of energy, such as ribosome formation, RNA and protein synthesis and lipids, as well as COVID-19, nonalcoholic fatty liver, neurodegenerative diseases and other disease pathways." (PMID 38617932, 2024).
hepatocellular carcinoma (1 paper, 2024). A malignant tumor that arises from hepatocytes. "Combined with ImmuCellAI database and TIMER2 database, the relationship between ARF5 expression and immune cell tumor infiltration in hepatocellular carcinoma (HCC) was analyzed." (PMID 38617932, 2024). "Through the Human Protein Atlas database, we learned about the expression of ARF5 in liver cells and related immune cells in human hepatocellular carcinoma tissues, and to determine the relationship between ARF5 and tumor immune microenvironment." (PMID 38617932, 2024). "Therefore, we will focus on the expression of ARF5 in hepatocellular carcinoma and its influence mechanism on tumor progression." (PMID 38617932, 2024). "In summary, we reported the high expression of ARFs family in most cancers, and further analyzed that the high expression of ARF5 leads to poor prognosis in hepatocellular carcinoma and may be involved in the regulation of the immune microenvironment of HCC." (PMID 38617932, 2024). "However, research on the clinical and pathological relevance of ARF5 in cancer, especially in hepatocellular carcinoma, still needs to be improved." (PMID 38617932, 2024). "Therefore, we further investigated the relationship between the expression of ARF5 and the level of related immune cell infiltration in hepatocellular carcinoma." (PMID 38617932, 2024). "There is currently no comprehensive report on the potential expression of the ARFs gene family in pan-cancer, as well as the clinical relevance and possible molecular regulatory mechanisms of ARF5 in cancer, especially in hepatocellular carcinoma (HCC)." (PMID 38617932, 2024).
liver cancer (1 paper, 2024). An epithelial or non-epithelial malignant neoplasm that arises from the liver. "In addition, we also analyzed the expression of ARF5 mRNA in human liver cells HL-7702 and liver cancer cell lines MHCC-97 and Huh7." (PMID 38617932, 2024).
nematode infections (1 paper, 2022). "Considering YUC4 synthesizes auxin while ARF5 responds to auxin, and that ARF5 is also significantly up-regulated during parasitic nematode infections, the possibility that YUC4 regulates ARF5 expression during RKN infection was investigated." (PMID 36466293, 2022).
Pan (1 paper, 2024). "Kaplan-Meier and Cox regression were used for prognostic analysis of ARF5 and Pan-cancer." (PMID 38617932, 2024).
poliovirus infection (1 paper, 2014). An disease or disorder caused by infection with Enterovirus C. "Arf1, Arf3, and Arf5 were reported to be activated upon poliovirus infection." (PMID 24911624, 2014).
cancer (8 papers, 2018 to 2025). A tumor composed of atypical neoplastic, often pleomorphic cells that invade other tissues. "After further analysis, we found that the high expression of ARF5 was significantly negatively correlated with the survival time of HCC patients such as OS, DFI, PFI and DSS, indicating that ARF5 is a cancer biomarker with great potential research value." (PMID 38617932, 2024). "In this study, we explored the expression of ARFs gene family in Pan-cancer as the starting point, selected the most closely related ARF5 in cancer development, and further screened out the most closely related HCC with ARF5." (PMID 38617932, 2024). "The results show that ARF5 does have a significant correlation with immune cells in most cancers, suggesting that ARF5 plays an important role in Pan-cancer." (PMID 38617932, 2024). "Meanwhile, PC1 negatively associated genes included FLNA, ARF5, and SLC25A6, suggesting its connection to cancer development." (PMID 32231683, 2020). "Therefore, we will focus on ARF5 gene to explore the relationship between its expression and cancer and its potential regulatory pathways." (PMID 38617932, 2024). "However, there are still few reports on the biological functions and molecular regulatory mechanisms of ARF5 in cancer, which needs to be filled in to explore the potential value of ARF5 in cancer screening and treatment." (PMID 38617932, 2024). "The conclusions of this study may provide a certain research foundation and new ideas for future cancer related research on ARF5." (PMID 38617932, 2024). "Simultaneously, depletion of ARF5 dramatically decreases the stemness of HCC cells and improves their sensitivity to cancer therapeutic agents." (PMID 40270615, 2025). "In this study, the expression levels of ARF6 and ARF5 in the serum of CRC patients were significantly reduced after exercise, reflecting the positive intervention effect of acute aerobic exercise on cancer patients." (PMID 40270615, 2025). "While its siblings, such as ARF1 and ARF5, have been widely investigated for their contributions to intracellular trafficking and organelle function, ARF6 has quietly been making waves in the field of cancer research." (PMID 40275490, 2025). "The cancer promoting effects of ARF1, ARF3, ARF4 and ARF6 in individual cancers have been studied, only the role of ARF5 in cancer has not been reported." (PMID 38617932, 2024). "ARFs family (ARF1, ARF3, ARF4, ARF5, ARF6) are generally highly expressed in Pan-cancer." (PMID 38617932, 2024). "ARF5 is a member of the human ARF gene family, which is involved in cell proliferation, motility and differentiation though regulation of cellular trafficking, cancer cell survival, migration and invasion." (PMID 37063865, 2023). "ARF5 is significantly highly expressed in 29 cancers, and the high expression of ARF5 in HCC patients is significantly negatively correlated with OS, DFI, PFI and DSS, which may lead to cancer deterioration by participating in tumor immune infiltration of HCC." (PMID 38617932, 2024). "The results are not surprising that the high expression of ARF5 predicts poor PFI and DSS in half of the cancers." (PMID 38617932, 2024).
infection (8 papers, 2012 to 2024). The state of being infected such as from the introduction of a foreign agent such as serum, vaccine, antigenic substance or organism. "Arf4 increased by 3–4 fold, whereas Arf5 almost doubled in amount at 4 hpi, and both Arfs remained elevated during the entire early phase of infection." (PMID 34440611, 2021). "Recent studies have shown that ARF4 and ARF5 are involved in distinct steps of the infection cycle of RNA viruses, demonstrating different functions for class II ARF proteins." (PMID 30655362, 2019). "As early as 10 min post infection, Arf6 was recruited to the plasma membrane at R. typhi entry foci, while Arf5 remained cytoplasmic." (PMID 26291822, 2015). "Since ARNO has been shown to activate Arf3 and Arf6 in vitro, we examined whether any additional Arf GTPases promote invasion by depleting Arf3, Arf4, Arf5, and Arf6 individually by siRNA transfection of HeLa cells 72 hr before infection with WT Salmonella." (PMID 22341462, 2012). "As demonstrated for the class I Arfs, Arf4, and Arf5 displayed a low level of endogenous expression and membrane recruitment in the MCMV-infected cells immediately after infection, similar to what was observed in the uninfected cells." (PMID 34440611, 2021). "This suggests YUC4 likely regulates late-stage RKN development within galls, but not the initial gall formation during early infection, unlike ARF5 which is known to prominently regulate gall formation frequency." (PMID 36466293, 2022). "and Arf3-, Arf4-, and Arf5-depleted cells, indicating normal progression of the immediate–early and early phases of infection in these cells." (PMID 34440611, 2021). "The specificity of the interactions between ARF5 and the three WRKYs was confirmed by co-expressing ARF3 (AT2G33860)-cYFP, which naturally lacks domain III and IV, and WRKY53-cYFP, expressed early after infection with A. tumefaciens strain C58 (3 hpi)." (PMID 25615824, 2015). "However, the activation pattern of pARF5::GFP did not concur with that of pARF5::ARF5-GUS at early infection stages." (PMID 36875577, 2023). "However, the same pARF5::ARF5-GUS line, with no evident expression in CN infection sites in this study, was strongly upregulated and functional in galls." (PMID 36875577, 2023). "The pARF5::ARF5-GUS line occasionally showed a pale GUS signal only in cells at the edge of the syncytia, but no clear signal within the syncytia at any of the infection stages analyzed (1, 3, 7, and 13 dpi), although it showed the expected activation pattern in uninfected roots." (PMID 36875577, 2023).
tumor (4 papers, 2018 to 2025). "This suggested that ARF5 might participate in the infiltration process of immune cells by promoting the activation of CD4+T cells, promoting immune escape of tumor cells, thereby promoting the progression of HCC and leading to malignant prognosis." (PMID 38617932, 2024). "Strikingly, IQSEC1, ARF5 and ARF6 increase similarly stratified patient survival when all tumour types were considered together, providing an exceptional >9-year (111 months) median survival increase for non-IQSEC1-ARF5/6-amplified patients (across 9307 patients)." (PMID 33712589, 2021).
ARF5 also shares sentences with these, for which no sentence is quoted: esophageal carcinoma (1 paper); neurodegenerative disease (1); nonalcoholic fatty liver (1); skin cutaneous melanoma (1).